LIFR (LIF receptor subunit alpha)
Diseases named in the same sentence as LIFR in open-access papers (continued):
Sharing a sentence is not in itself a finding about the gene and the disease.
breast cancer (continued). "Consequently, LIFR downregulation promotes human MCF7 breast cancer cell emergence from dormancy in the bone." (PMID 33828987, 2021). "Similar to endometriosis, the LIFR was downregulated in breast cancer." (PMID 32245259, 2020). "Both functions of LIFR have been recognized in breast cancer." (PMID 32651426, 2020). "In SUM159 human breast cancer cells, the knockdown of LIFR dramatically increased the ability of tumor cells to colonize the lungs, while ectopic LIFR expression in 4T1 mouse mammary carcinoma cells significantly reduced the ability of these cells to colonize the lungs." (PMID 32023849, 2020). "While studies have confirmed that the loss of LIFR:STAT3 signaling is associated with reduced breast cancer patient survival, to date, there are no clinical studies that have rigorously tested these cytokines and their receptors in the oncology setting." (PMID 32023849, 2020). "Interestingly, treatment with LIFR ligand leukaemia inhibitory factor (LIF) and ectopic LIFR expression act as metastasis suppressors in breast cancer." (PMID 32707998, 2020). "Interestingly, the restoration of LIFR in highly aggressive MDA-MB-231 cells by treatment with a histone deacetylase inhibitor restores STAT3 signaling downstream of LIF:LIFR, which has been proposed to promote drug resistance by breast cancer cells." (PMID 32023849, 2020). "Finally, in breast cancer patients, low LIFR levels were shown to correlate with poor prognosis and with the appearance of overt metastasis along with the loss of CSC-associated genes." (PMID 33193295, 2020). "Finally, high LIFR expression in breast cancer has also been correlated with better overall survival (OS)." (PMID 32245259, 2020). "LIF/LIFR signalling was described as being upstream the Hippo pathway in breast cancer." (PMID 32707998, 2020). "These cytokines can complex with LIFR on breast cancer cells, which promotes dormancy in bone-disseminated tumor cells, and is therefore highly relevant to the pathogenesis of bone-disseminated breast cancer cells." (PMID 32023849, 2020). "Other examples proving the molecular similarity between dormant DCCs and CSCs include the interleukin 6 (IL-6) cytokine leukemia inhibitory factor (LIF)-LIF receptor (LIFR) axis, which appears to have a role in preserving both dormancy and cancer stemness, at least in the breast cancer setting." (PMID 33193295, 2020). "In breast cancer, LIFR is a tumor suppressor and metastasis suppressor gene." (PMID 33505963, 2020). "Similarly, LIFR inhibition suppressed metastasis of pancreatic carcinoma and rhabdomyosarcoma, reduced stemness and growth of ovarian and breast cancers, and promoted apoptosis." (PMID 32651426, 2020). "Likewise, nuclear PAK4 represses the expression of LIFR to promote the bone metastasis of ER positive breast cancer cells." (PMID 32549768, 2020). "In addition, we found that nPAK4-ERα axis contributes to breast-to-bone metastasis in ERα+ breast cancer via antagonizing the activity of a breast cancer bone metastasis suppressor, leukemia inhibitory factor receptor (LIFR)." (PMID 30177834, 2019). "Furthermore, the activation of TEAD target gene, CTGF, mediates the metastatic colonization of breast cancer through leukemia inhibitory factor receptor (LIFR) suppression." (PMID 31212916, 2019). "Together, these findings established that nPAK4 is a potent endogenous repressor of the ERα transactivation function and that nPAK4 may repress the expression of the ERα-induced gene LIFR in breast cancer cells, leading to bone metastasis." (PMID 30177834, 2019). "Moreover, TAZ is indirectly tied to breast cancer stemness after the finding that revealed that miRNA125, by targeting the Hippo pathway and activator leukemia inhibitory factor receptor (LIFR), induces TAZ activity and breast cancer stemness." (PMID 30619734, 2018). "Furthermore, LIFR functions as a potential metastasis suppressor in human breast cancer cells through activation of the Hippo-YAP pathway." (PMID 30504771, 2018).
breast cancer (continued). "Moreover, LIFR expression is down regulated in breast cancer and also significantly correlates with poor prognosis and overall survival outcomes of breast cancer patients." (PMID 30012200, 2018). "LIFR has been identified as a metastasis suppressor of breast cancer via the HIPPO-YAP pathway." (PMID 30012200, 2018). "The present study shows the independent predictive effect of miR-629-3p on lung metastasis in TNBC and reveals that the suppression of miR-629-3p attenuates pulmonary metastasis in experimental breast cancer by directly targeting LIFR, which is an inhibitor of multiple metastatic signaling pathways." (PMID 28629464, 2017). "In addition, expression of LIFR inversely correlated with metastasis and clinical outcomes of breast cancer patients." (PMID 25749520, 2015). "LIFR is a known tumor suppressor in breast cancer and an upstream regulator of Hippo signaling." (PMID 25962054, 2015). "However, inverse relationship between miR-125a and LIFR were observed in other breast cancer cell lines also." (PMID 25962054, 2015). "LIFr signaling is upstream of the Hippo-YAP pathway in breast cancer metastasis." (PMID 26329521, 2015). "LIFR has been identified as a tumor suppressor in breast cancer." (PMID 25962054, 2015). "In breast cancer, hypoxia induces dormancy in the primary site and in DTCs, and cells remain dormant even once hypoxia is removed, however prolonged hypoxia downregulates LIF receptor (LIFR) triggering escape from dormancy and formation of bone micrometastases." (PMID 41091336, 2025). "Finally, LIFR signaling blockade by hypoxia may allow breast cancer cells to exit dormancy in the bone marrow to proliferate and give rise to metastasis." (PMID 35163731, 2022). "Our data further indicate that blocking the LIF/LIFR signaling pathway could decrease cancer stemness in breast cancer cells, which points to a potential clinical application of targeted therapy using a LIFR inhibitor for breast cancer cells." (PMID 34947829, 2021). "LIFR overexpression may also confer dormancy in breast cancer metastases to the bone." (PMID 32245259, 2020). "Notably, down regulation or loss of LIFR is related to poor prognosis in most nonmetastatic stage I–III breast cancer." (PMID 31781173, 2019). "LIFr was recently identified as a significant prognostic factor in human breast carcinoma, and blockade of LIFr inhibits the chemotaxis of rhabdomyosarcoma cells, suggesting that LIFr activation may promote metastasis and increase the invasive potential of solid tumors." (PMID 26329521, 2015). "For example, EC359 had little efficacy against ER+ breast cancer cells, such as MCF7, which express low amounts of LIF and LIFR." (PMID 40075639, 2025). "Ectopic expression of LIFR in 4T1 and MDA-MB-231 metastatic cells have been shown to inhibit breast cancer cell invasion and migration." (PMID 39709500, 2024). "For example, EC359 shows little efficacy against ER+ breast cancer cells, such as MCF7, which express minimal amounts of LIF and LIFR." (PMID 39518071, 2024). "LIFR is known to activate STAT3, ERK, and AKT signaling, among numerous other signaling pathways in breast cancer." (PMID 38409028, 2024). "Binding of ILEI to the LIF receptor (LIFR) activates STAT3 and leads to EMT and stem cell formation in a breast cancer model." (PMID 37226685, 2023). "In contrast, overexpression of LIFR in hepatocellular carcinoma (HCC) and breast cancer (BC) inhibited cancer cell migration and invasion in vivo and in vitro." (PMID 35581376, 2022). "Supporting these findings, it has been reported that breast cancer cells with low metastatic potential, such as MCF-7, express functional LIFR, but breast cancer cells that aggressively colonize the lung or bone, like MDA-MB231, lack a functional LIFR." (PMID 35163731, 2022). "In breast cancer, knockdown of PCBP1 enhances the stemness of breast cancer cells and promotes breast cancer invasion and metastasis by regulating the ILEI/LIFR signalling pathway." (PMID 35907982, 2022).
breast cancer (continued). "LIF receptor (LIFR), an upstream regulator of Hippo signalling, has an inversely expressed in relation with miR-125a in human breast cancer stem cells." (PMID 34832867, 2021). "LIF: The LIF receptor (LIFR) was identified as a breast tumor suppressor by an shRNA screen and shown to function as a breast cancer lung metastasis suppressor by a second laboratory." (PMID 32023849, 2020). "The Hippo pathway has been implicated in gastric CSC properties and was shown to be regulated by leukaemia inhibitory factor receptor (LIFR) and its ligand LIF in breast cancer." (PMID 32707998, 2020). "It has been previously established that LIFR expression on breast cancer cells promotes tumor dormancy in the bone marrow and that several of the gp130 cytokines (LIF, OSM, and CNTF) are able to signal through LIFR." (PMID 32023849, 2020). "Whereas OSM binding to the OSMR has been shown to promote cancer cell malignancy and reduce long-term survival in patients with breast cancer, LIF activation of the LIFR suppresses tumor growth and metastasis." (PMID 29898744, 2018). "Down-regulation of LIFR expression was also observed in several types of cancer and it was identified as tumor suppressor in both HCC and breast cancer." (PMID 25749520, 2015). "In total cell population, the basal transcript levels of LIFR in MCF7 and primary breast cancer cells were low when compared to MCF12A cells.." (PMID 25962054, 2015). "The basal transcript expression level of LIFR in MCF7 and primary breast cancer stem cells was similar to MCF12A stem cells." (PMID 25962054, 2015). "In bone metastases of breast cancer, LIFR knockdown disrupts the dormancy phenotype, with STAT3 being an essential factor in LIFR signaling, and LIF upholds the dormancy phenotype through the LIFR: STAT3: SOCS3 pathway." (PMID 40977686, 2025). "Small-molecule inhibitors that target LIF/LIFR, such as EC359 and EC330, were used to treat ovarian cancer (OCa), breast cancer, and endometrial cancer (ECa), which inhibited tumor development in OCa cells, ECa cells, and breast cancer MCF7 cells." (PMID 38672566, 2024). "On the other hand, lack of LIFR induces migration, invasion, and metastases in nonmetastatic breast cancer cells via activating YAP." (PMID 37692482, 2024). "LIFR was found to be downregulated in breast cancer cells, and LIFR expression exhibited a negative correlation with the likelihood of breast cancer metastasis." (PMID 37256184, 2023). "Our previous studies have clearly demonstrated the role of shPCBP1-mediated EMT in the progression of mammary carcinoma in vivo and was therefore selected as an appropriate experimental context for further characterization of FAM3C/LIFR/STAT3 participation in the regulation of pathological features." (PMID 37927213, 2023). "In addition, the results indicate that activation of LIFR signaling in breast cancer cells in the existence of CAF-secreted LIF can induce Nanog and Oct4 expression and increase breast cancer stem cell markers CD24−/CD44+." (PMID 34947829, 2021). "LIF binds to LIF receptor (LIFR), which has been shown to be downregulated in patients with breast cancer bone metastasis.Of note, several key bone cells including osteoblasts, osteoclasts, chondrocytes and adipocytes secrete LIF and also express corresponding receptors." (PMID 33809315, 2021). "Apart from its anti-metastatic effect in breast cancer, recent studies showed that LIF/LIFR signalling could negatively regulate metastasis of pancreatic cancer (PC) and hepatocellular carcinoma (HCC) cells both in vitro and in vivo." (PMID 32707998, 2020). "While ER+ breast cancer cell lines were used in the initial screens for LIF and LIFR in these studies, functional studies were all carried out in TNBC cell lines, so it is unclear whether EC359 would have had similar effects on ER+ tumor progression in vivo." (PMID 32023849, 2020). "Activation of the LIFR by OSM promotes bone growth and may also suppress breast cancer metastatic phenotypes." (PMID 29898744, 2018).
breast cancer (continued). "In agreement with previous studies, our results also showed a significant downregulation of LIFR in breast cancer cells compared to nonmalignant breast epithelial cells." (PMID 25962054, 2015). "Activation of YAP1 in the ER- cell line SUM159 mediated by LIFR (leukemia inhibitory factor receptor) repression resulted in substantial lung metastases in nude mice, again suggesting an oncogenic role of YAP1 in ER- breast cancer." (PMID 24559095, 2014). "In addition, it has been shown that rapamycin, an inhibitor of the mTOR pathway, suppresses the promoting effect of LIF on tumorigenesis and metastasis in breast cancer cells and that combined immunization against LIF and LIFR inhibits tumor formation from mammary CSCs in BALB/c mice." (PMID 35163731, 2022). "In breast cancer, LIFR has been identified as a tumor suppressor and a negative regulator of YAP29." (PMID 30504771, 2018). "Additionally, they found that breast cancer cells which aggressively colonize the lung also lack a functional LIFR and do not respond to LIF in vitro." (PMID 28629464, 2017). "Furthermore, our data demonstrated that suppression of LIFR in nonmalignant breast epithelial cells resulted in an increased stem cell percentage, and an inverse effect was observed in LIFR overexpressing breast cancer epithelial cells." (PMID 25962054, 2015). "Consequently, the downregulated LIFR promoted MCF-7 cell exit from dormancy, suggesting that inducing and maintaining LIFR, a downstream factor of PTHrP/PTH1R, might keep tumor cells in a dormant state to prevent overt bone metastasis in breast cancer." (PMID 37046642, 2023). "However, since these studies made use of the MDA-MB-231 breast cancer cell line, which several groups have shown does not express a functional LIFR, it is unclear how LIF may stimulate the migration and invasion of these cells in vitro." (PMID 32023849, 2020). "Although LIFr can diminish YAP phosphorylation and induce its cytoplasmic retention in breast cancer cells, suppressing LIFr in melanoma cells did not inhibit YAP phosphorylation or decrease YAP mRNA expression." (PMID 26329521, 2015). "Notably, detectable levels of LIFR expression are found only in non-metastatic breast cancer cell lines, such as SUM149, SUM159, MCF7, T47D, and SUM229, whereas in metastatic breast cancer cells, MDA-MB-231 and SUM1315 are not detectable." (PMID 39709500, 2024). "Since the status of OSMR on breast cancer cell lines has not been fully elucidated yet, the effects of OSM could be delineated between the expression and functionality of OSMR and LIFR in such cell lines." (PMID 32023849, 2020). "However, OSM can signal through both LIFR and OSMR to induce downstream signaling, and the function of OSM:LIFR and OSM:OSMR signaling in breast cancer cells has not been fully explored." (PMID 32023849, 2020).
pancreatic cancer (19 papers, 2015 to 2025). "A low LIFR expression was associated with shorter survival in pancreatic cancer and NSCLC patients with mutated KRAS." (PMID 36793597, 2023). "The expression of leukemia inhibitory factor receptor (LIFR) was significantly lower in pancreatic cancer compared to some cancers, but inhibition of KRAS mutation upregulated LIFR expression and was accompanied by a decrease in GLUT1 expression." (PMID 37152291, 2023). "Another study, however, showed that expression of LIFR was associated with longer overall survival of pancreatic cancer patients." (PMID 35159011, 2022). "Furthermore, in pancreatic cancer tissue microarrays, downregulated LIFR was significantly associated with Tumour Node Metastasis (TNM) stage and lymph node metastasis, and silencing of LIFR in-vitro reduced colony formation and metastatic potential of pancreatic cancer cells." (PMID 30263091, 2018). "Previous investigations have also suggested that the regulatory role of LIFR in glycolysis is markedly important in the progression of gastric cancer, pancreatic cancer, and lung cancer, which corroborates our findings." (PMID 41272827, 2025). "In pancreatic cancer, LIF secreted by CAFs binds to LIFR on the surface of pancreatic cancer cells and then activates the downstream STAT3 signaling pathway to play its biological role in promoting the progression of pancreatic cancer and chemoresistance." (PMID 40751418, 2025). "Together, these data demonstrate that LIFR inhibition reverses pancreatic cancer cell proliferation and EMT promoted by LIF/LIFR signalling." (PMID 36359879, 2022). "In the present study, we developed an in silico strategy to support the repositioning of mifepristone as a LIFR antagonist and confirmed the computational data by in vitro studies on pancreatic cancer cell lines." (PMID 36359879, 2022). "Further clarification is needed to understand the precise role of LIF/LIFR signaling in pancreatic cancer." (PMID 35159011, 2022). "In PSC-conditioned medium-stimulated human pancreatic cancer cells, LIF receptor (LIFR) and its co-receptor IL-6 signal transducer (IL6ST, also known as gp130) are only receptors identified as interacting partners with STAT3 (immunoprecipitation)." (PMID 33572223, 2021). "LIFR inhibition has already been found to effectively block LIF-induced perineural invasion in pancreatic cancer cell lines and in mouse models." (PMID 33630157, 2021). "Conditional deletion of LIFR leads to reduced pancreatic tumor progression and prolonged survival in a pancreatic cancer mouse model (Pdx1-Cre; lox-stop-lox-KrasG12D/+; Trp53lox/lox; Lifrlox/lox; lox-stop-lox-Rosa26Luc/Luc)." (PMID 33572223, 2021). "As a paracrine factor, LIF binds to the heterodimer of LIFR and gp130 on the surface of pancreatic cancer cells, activates the JAK/STAT3 pathway and ultimately induces transcription of genes which are known to regulate cell cycle, apoptosis, angiogenesis and invasion." (PMID 33630157, 2021). "LIFR belongs to the gp130 receptor family, which has been recognized as a tumor suppressor gene in multiple types of cancers, including breast, hepatocellular, and pancreatic cancers." (PMID 28629464, 2017). "Since LIFr expression was increased in melanoma when compared to nevi, and LIF signaling is linked to proliferation of breast, kidney, prostate and pancreas carcinoma cells, we hypothesized that LIFr expression affects melanoma cell growth." (PMID 26329521, 2015). "Several studies support the suppression of LIFR signalling as potential target in inhibiting cell growth and tumour progression, and we have shown recently, that LIFR-mediated antagonism supports the anti-oncogenic effect of mifepristone in pancreatic cancer and chemoresistance." (PMID 36998446, 2023). "Encouragingly, the first-in-human clinical trial that combined the anti-LIFR antibody EC359 and GEM to target pancreatic tumor stroma and cancer cells was supported by the National Institute of Health." (PMID 35045883, 2022).